FA2H (fatty acid 2-hydroxylase)
Description:
Catalyzes the hydroxylation of free fatty acids at the C-2 position to produce 2-hydroxy fatty acids, which are building blocks of sphingolipids and glycosphingolipids common in neural tissue and epidermis. FA2H is stereospecific for the production of (R)-2-hydroxy fatty acids. Plays an essential role in the synthesis of galactosphingolipids of the myelin sheath (By similarity). Responsible for the synthesis of sphingolipids and glycosphingolipids involved in the formation of epidermal lamellar bodies critical for skin permeability barrier. Participates in the synthesis of glycosphingolipids and a fraction of type II wax diesters in sebaceous gland, specifically regulating hair follicle homeostasis (By similarity). Involved in the synthesis of sphingolipids of plasma membrane rafts, controlling lipid raft mobility and trafficking of raft-associated proteins (By similarity).
Synonyms: FAAH; FAXDC1; FLJ25287; FAH1; SCS7; SPG35
Tractability: Antibody: UniProt predicts a signal peptide or a membrane-spanning region. PROTAC: ubiquitination databases record sites on it.
Target class: Enzyme; Oxidoreductase
Gene: Protein-coding gene on chromosome 16 (74,712,955 to 74,774,837, reverse strand). Ensembl gene ENSG00000103089.
Subcellular location: Endoplasmic reticulum membrane; Microsome membrane
Subcellular location (Human Protein Atlas): Nuclear membrane
Pathways (Reactome):
Metabolism: Sphingolipid de novo biosynthesis
Gene Ontology:
Molecular function: 4-hydroxysphinganine ceramide fatty acyl 2-hydroxylase activity; fatty acid 2-hydroxylase activity; free fatty acid 2-hydroxylase activity; protein binding; heme binding
Biological process: ceramide biosynthetic process; establishment of skin barrier; galactosylceramide biosynthetic process; glucosylceramide biosynthetic process; plasma membrane raft organization; sphingolipid biosynthetic process; fatty acid metabolic process; lipid metabolic process
Cellular component: membrane; endoplasmic reticulum membrane; endoplasmic reticulum
Genetic constraint (gnomAD): Loss-of-function variants: 18 observed, 35.17 expected, observed/expected ratio (o/e) 0.51, 90% interval 0.35 to 0.76. The synonymous counts are far from expectation, so gnomAD's model fits this gene poorly and the ratio says little. Missense variants: 486 observed, 435.46 expected, observed/expected ratio (o/e) 1.12, 90% interval 1.03 to 1.2. Synonymous variants: 241 observed, 181.59 expected, observed/expected ratio (o/e) 1.33, 90% interval 1.19 to 1.48.
Gene-disease validity (ClinGen):
ClinGen rates the evidence that FA2H causes each of these diseases.
hereditary spastic paraplegia 35 (autosomal recessive): Definitive.
Homologues: Orthologues: chimpanzee FA2H (99% identical), macaque FA2H (97% identical), rabbit FA2H (88% identical), pig FA2H (83% identical), mouse Fa2h (83% identical), guinea pig FA2H (82% identical), dog FA2H (81% identical), rat Fa2h (81% identical), tropical clawed frog fa2h (60% identical), zebrafish fa2h (56% identical), Caenorhabditis elegans fath-1 (34% identical), Drosophila melanogaster Fa2h (32% identical).
Diseases named in the same sentence as FA2H in open-access papers:
FA2H is named in the same sentence as 85 diseases in open-access papers, as found by Europe PMC text mining. Sharing a sentence is not in itself a finding about the gene and the disease. The quoted sentences say what the papers report.
leukodystrophy (14 papers, 2012 to 2025). Leukodystrophies are a group of rare, progressive, metabolic, genetic diseases that affect the brain, spinal cord and often the peripheral nerves. "FA2H deficiency leads to leukodystrophy and hereditary spastic paraplegia in humans and FA2H deficient mice show an initially normal myelin formation but leukodystrophy phenotype at a later age." (PMID 37890668, 2023). "Fa2h is responsible for the formation of 2-hydroxy galactolipids in nervous system myelin, and its mutations cause leukodystrophy and spastic paraplegia." (PMID 36543780, 2022). "Fatty acid 2 hydroxylase (FA2H) mutations are linked to leukodystrophy, hereditary spastic paraplegia (SPG35) and NBIA." (PMID 25870938, 2016). "In turn, FA2H deficiency results in abnormal myelin, giving rise to the allelic disorders leukodystrophy and the HSP subform SPG35." (PMID 23814539, 2013). "In addition to FAHN (OMIM #611026), mutations in FA2H have also been associated with leukodystrophy (OMIM #612319) and hereditary spastic paraplegia (HSP) type SPG35 (OMIM #612319)." (PMID 40862740, 2025). "In humans, mutations in FA2H (OMIM611026) are associated with recessively inherited spastic paraplegia type 35, leukodystrophy with spasticity and dystonia, and fatty acid hydroxylase-associated neurodegeneration, a rare subtype neurodegeneration with brain iron accumulation." (PMID 34599683, 2021). "Mutations in the FA2H-gene lead to leukodystrophy with spastic paresis and dystonia." (PMID 28467360, 2017). "Mutations in the fatty acid 2-hydroxylase gene, FA2H, have been associated with leukodystrophy and spastic paraparesis, underscoring the importance of OH-ceramides in the nervous system." (PMID 31068772, 2019).
hereditary spastic paraplegia (13 papers, 2014 to 2025). Hereditary spastic paraplegias (HSP) comprise a genetically and clinically heterogeneous group of neurodegenerative disorders characterized by progressive spasticity and hyperreflexia of the lower limbs. "Deficiency in FA2H causes a human disease known as fatty acid hydroxylase-associated neurodegeneration (FAHN) or hereditary spastic paraplegia (HSP) type 35/spastic paraplegia 35 (HSP35 or SPG35)." (PMID 36902339, 2023). "Mutations in the fatty acid 2-hydroxylase are associated with hereditary spastic paraparesis, and mutations in lysosomal acid ceramidase (that removes the headgroup from 2-hydroxy sphingolipids in the Lys), cause a lysosomal disorder, Farber’s disease." (PMID 31068772, 2019). "Interestingly, a second homozygous mutation in the FA2H gene, implicated in Hereditary spastic paraplegia, was revealed, appearing to have contributed to the novel phenotype observed, and highlighting a potential interaction between the two mutated genes." (PMID 31191442, 2019). "Other forms of early-onset Hereditary Spastic Paraplegia may present with a similar clinical profile, such as SPG35 (FA2H), SPG79B (UCHL1), SPG11, and SPG15 (usually with even more complicated phenotypes)." (PMID 40757543, 2024). "Additionally, FA2H is also involved in familial leukodystrophy and hereditary spastic paraplegia (SPG35)." (PMID 33092153, 2020). "Of note, there are nine genes among these targets that when mutated are known causes for inherited peripheral neuropathies (IPN) and hereditary spastic paraplegia (HSP) (Inf2, Sox10, Wnk1, Med25, Fa2h, Bscl2, Slc12a6, Kif1a and Kif5a)." (PMID 28077174, 2017).
breast carcinoma (9 papers, 2019 to 2024). "Here we speculated that the gain or loss of enhancer-promoter interactions and their corresponding DEGs such as up-regulated JRKL and down-regulate FA2H may constitute potential diagnostic or therapeutic targets for reversing doxorubicin resistance in breast cancer." (PMID 36003143, 2022). "Altered FA2H expression may be associated with resistance to treatment and the progression of tumor growth, for example, in lung, ovarian, colorectal, and breast cancer." (PMID 36230546, 2022). "These authors further demonstrated that FA2H suppresses cancer stemness in breast cancer cells by inhibiting the STAT3/IL6 axis and NFkB signalling." (PMID 39233332, 2024). "This later showed that THC not only increases the expression of fatty acid 2-hydroxylase (FA2H) via the upregulation of PPARα expression in human breast cancer MDA-MB-231 cells but that THC also interferes with the PPARβ/δ-mediated inhibition of PPARα." (PMID 33498245, 2021). "In MDA-MB-231 breast cancer cells, THC was shown to cause fatty acid 2-hydroxylase (FA2H) induction." (PMID 32708138, 2020). "Hirao-Suzuki (2019) showed that Δ9-THC increases fatty acid 2-hydroxylase (FA2H) expression in human breast cancer cells." (PMID 32458627, 2020). "As CSCs are known responsible for tumor resistance to drugs and radiation, FA2H likely plays a tumor suppressive role controlling CSC signalings in breast cancers." (PMID 31709178, 2019). "Likewise, a tumor suppressive role has been proposed for FA2H in breast cancer." (PMID 36630049, 2023). "Both qRT-PCR and western blotting results showed that FA2H could clearly distinguish the 12 breast cancer cell lines while the rest candidate genes could not." (PMID 31709178, 2019).
fatty acid hydroxylase-associated neurodegeneration (8 papers, 2014 to 2026). "Deficiency in FA2H causes a neurodegenerative disease known as hereditary spastic paraplegia 35 (HSP35/SPG35) or fatty acid hydroxylase-associated neurodegeneration (FAHN)." (PMID 36902339, 2023). "Mutations in FA2H (fatty acid 2-hydroxylase) cause AR fatty acid hydroxylase-associated neurodegeneration (FAHN)." (PMID 33092153, 2020). "Another NBIA-gene with a role in lipid metabolism is FA2H (fatty acid 2-hydroxylase), whose mutations lay at the basis of Fatty Acid Hydroxylase-Associated Neurodegeneration (FAHN), a rare autosomal recessive disease with an estimated prevalence lower than one in one million." (PMID 39195264, 2024).
Dystonia (7 papers, 2016 to 2022). An abnormally increased muscular tone that causes fixed abnormal postures. "For example, autosomal recessive mutations in fatty acid 2-hydroxylase (FA2H), which catalyzes the hydroxylation of ceramide at position 2 of the N-acyl chain, result in HSP type 35, which is characterized by early-onset progressive spasticity, ataxia, dystonia and cognitive decline." (PMID 29163032, 2017). "Defective FA2H also leads to object neurodegeneration with brain iron accumulation (NBIA), a spectrum disorder with phenotypes ranging from infantile with early death to adult-onset parkinsonism-dystonia." (PMID 29163032, 2017).
Spastic paraplegia (7 papers, 2019 to 2025). Complete loss of the ability to move the lower limbs accompanied by spasticity of the lower limbs. "On the other hand, hydroxylated fatty acids are also important in the context of myelin sheath formation since mutations to the fatty acid hydroxylating FA2H cause relevant neurological abnormalities and provoke spastic paraplegia (SPG35)." (PMID 34940418, 2021). "Indeed, mutations in FA2H cause autosomal recessive leukodystrophy with spastic paraplegia in humans and mice." (PMID 36441023, 2022). "Another example is spastic paraplegia (SPG35), which is caused by mutation of the enzyme fatty acid 2-hydroxylase (FA2H), the enzyme that produces C2-hydroxylated fatty acids." (PMID 34940418, 2021).
Ataxia (4 papers, 2017 to 2025). Ataxia refers to impaired coordination of voluntary muscle movement. "In our study, we identified a known variant in HEXB in one family with Sandhoff disease, and a new variant in FA2H causing ataxia with cognitive impairment." (PMID 35326432, 2022). "For example, pathogenic variants in the ceramide synthase gene CERS2 cause epilepsy and ataxia, and mutations in genes involved in sphingolipid metabolism such as B4GALNT1, GBA2, and even FA2H, cause different forms of spasticity and ataxia, such as SPG26, SPG46, and SPG35, respectively." (PMID 38911600, 2024).
gastric cancer (4 papers, 2022 to 2023). A primary or metastatic malignant neoplasm involving the stomach. "On the other hand, FA2H inhibition resulted in reduced growth and enhanced cisplatin sensitivity of gastric cancer cells." (PMID 36630049, 2023). "Reduced expression of fatty acid 2-hydroxylase, the enzyme that catalyzes hydroxylation of free fatty acids prior to their incorporation into 2-hydroxylated sphingolipids, was detected in tumor tissue from colorectal and gastric cancer patients." (PMID 35851093, 2022). "Especially, previous studies found that FA2H (Fatty acid 2-hydroxylase) depletion could lead to decreased chemosensitivity to cisplatin via inhibition of AMPK and activation of mTOR/S6K1/Gli1 pathway in gastric cancer, and turn different cancer cells resistant to PM02734." (PMID 36003143, 2022).
aceruloplasminemia (3 papers, 2020 to 2024). An adult-onset disorder of neurodegeneration with brain iron accumulation (NBIA) characterized by anemia, retinal degeneration, diabetes and various neurological symptoms. "FAHN (fatty acid hydroxylase-associated neurodegeneration; FA2H gene), NF (neuroferrinopathy; FTL gene), aceruloplasminemia (CP gene) and Woodhouse–Sakati syndrome (DCAF17 gene) are rare types." (PMID 33092153, 2020). "The abnormal brain iron accumulation in the basal ganglia was also observed in other disorders, such as Kufor-Rakeb syndrome (KRS), Aceruloplasminemia (ACEP), Spastic paraplegia 35 (SPG35), and Jaberi-Elahi syndrome (JABELS), which were caused by mutated ATP13A2, CP, FA2H, GTPBP2, respectively." (PMID 38765101, 2024).
alopecia (3 papers, 2021 to 2023). Hair loss usually from the scalp. "Moreover, in Fa2h−/− mice, deficiency in Fa2h caused a delay in emergence of the fur during morphogenesis and depilation-induced anagen and a cyclic alopecia." (PMID 34599683, 2021). "Downregulation of FA2H may disrupt synthesis of 2-hydroxylated glucosylceramide and wax diesters in sebaceous gland and cause delayed hair fiber from follicles, hyperproliferation and cyclic alopecia." (PMID 35524260, 2022).
atherosclerosis (3 papers, 2021 to 2022). A disease characterized by the build-up of fatty material and calcium deposition in the arterial wall resulting in partial or complete occlusion of the arterial lumen. "For example, through binding mixed lineage kinase domain-like protein (MLKL)promoter, lncRNA FA2H-2 regulates autophagy and inflammation in atherosclerosis.After the suppression of MLKL expression in SMCs and ECs in response to ox-LDL,autophagic flux is enhanced and inflammation is diminished." (PMID 39077721, 2022).
Cognitive impairment (2 papers, 2022 to 2025). Abnormal cognition is characterized by deficits in thinking, reasoning, or remembering. "For example, mental retardation in SPG15/ZFYVE26 and SPG46/GBA2, cognitive impairment and epilepsy in SPG35/FA2H and SPG84/PI4KA." (PMID 39932116, 2025).
Intellectual disability (2 papers, 2013 to 2025). "Specifically, exome sequencing of the probands and their parents would have helped to determine if additional mutations in genes related to autism or intellectual disability or in the same pathway than FA2H, might be involved in the families we presented." (PMID 24299421, 2013).
Obesity (2 papers, 2014 to 2023). Accumulation of substantial excess body fat. "FA2H may be a factor involved in obesity-induced insulin resistance as FA2H downregulation through the micro-RNA miR-3075 led to enhanced insulin signaling." (PMID 36902339, 2023).
ovarian carcinoma (2 papers, 2023 to 2025). A malignant neoplasm originating from the surface ovarian epithelium. "FA2H,while traditionally recognized for its role in lipid metabolism, has recently been implicated in cancer biology, particularly in ovarian cancer." (PMID 40510341, 2025). "Research indicates that lower FA2H expression is linked to worse outcomes in ovarian cancer, suggesting its role as a tumor growth inhibitor." (PMID 40510341, 2025). "FA2H is suggested to be used as a biomarker and a therapeutic target for breast and ovarian cancer." (PMID 36846236, 2023).
prostate carcinoma (2 papers, 2020 to 2023). A carcinoma that arises from epithelial cells of the prostate gland. "FAM72D, ARHGAP33, TACR2, PLEK2, and FA2H were identified as independent prognosis factors in prostate cancer patients." (PMID 32566639, 2020).
triple-negative breast carcinoma (2 papers, 2019 to 2020). An invasive breast carcinoma which is negative for expression of estrogen receptor (ER), progesterone receptor (PR), and human epidermal growth factor receptor 2 (HER2). "FA2H and other candidates unveiled in this study that capture the features of cancer stem cells may contribute as diagnostic marker and/or effective therapeutic targets for improved triple negative breast cancer management." (PMID 31709178, 2019). "Higher levels of FA2H expression has been reported to be a crucial biomarker that is related to the prognosis of patients with triple-negative breast cancer, where higher levels of FA2H has been shown to result in shorter disease-free survival." (PMID 32708138, 2020). "These are supportive of our observation that FA2H is significantly suppressed in triple negative breast cancer cell lines." (PMID 31709178, 2019). "We, thus, hypothesize that the CXCR2/IL6 axis plays a synergistic role with FA2H in breast CSC signaling and, possibly and in particular, among triple negative breast cancers." (PMID 31709178, 2019).
cystitis (1 paper, 2021). Inflammation of the urinary bladder. "Furthermore, reported expression of FA2H transcripts in the urinary tract supports the associated urolithiasis and cystitis seen in some of the IC-affected cattle." (PMID 34599683, 2021).
esophageal cancer (1 paper, 2022). A primary or metastatic malignant neoplasm involving the esophagus. "Of note, cox hazards ratio analysis indicated higher expression of FA2H indicated an increased risk of esophageal cancer in the survival analysis than other three metabolic genes, strongly suggesting that predominant role of FA2H in esophageal cancer progression." (PMID 36274060, 2022). "The metabolism gene signature, consisting of four shared metabolic hub genes (i.e., FA2H, ICAM1, F3, and CYBA), was further identified to be remarkably elevated in TCGA esophageal cancer tissues compared with combined normal tissues from both TCGA and GTEx dataset." (PMID 36274060, 2022). "In addition, co-amplification of FOXC2 and FA2H was observed in 185 patients with esophageal cancer from TCGA cohort, whereas no prominent correlation was found between FA2H and the other three TFs." (PMID 36274060, 2022).
gastric tumor (1 paper, 2020). "Fatty acid 2-hydroxylase (FA2H) was shown to play a crucial role in regulating hedgehog signaling and the suppression of gastric tumor growth." (PMID 32566639, 2020).
glioma (1 paper, 2024). A benign or malignant brain and spinal cord tumor that arises from glial cells (astrocytes, oligodendrocytes, ependymal cells). "Relative quantitation of GSLs across multiple structural levels provides evidence of dysregulated gene and protein expressions of FA2H and CerS2 in human glioma tissue." (PMID 38965283, 2024). "FA2H which is responsible for adding an OH group at the C2 position on fatty acids and CerS2 which prefers to assemble C24-CoA to the long chain base are both down-regulated at transcription and protein levels in glioma tissue." (PMID 38965283, 2024). "Indeed, in glioma tissue samples the mRNA and the protein level of FA2H were significantly lower, explaining the metabolic origin of reduced amount of GSLs containing hFA." (PMID 38965283, 2024).
hepatocellular carcinoma (1 paper, 2021). A malignant tumor that arises from hepatocytes. "The results indicate that elevated interpretation of A-Raf and FA2H in hepatocellular carcinoma is associated with lipid metabolism disorders and cancer progression." (PMID 34651050, 2021).
Hyperglycemia (1 paper, 2024). An increased concentration of glucose in the blood. "The increased anaerobic glycolytic flux, independent of glucose levels, impairs GSIS during postprandial hyperglycemia, which could be due to the suppressed FA2H expression by hypoxia." (PMID 39442620, 2024).